IL1B (interleukin 1 beta)
Diseases named in the same sentence as IL1B in open-access papers (continued):
Sharing a sentence is not in itself a finding about the gene and the disease.
Myocardial fibrosis (57 papers, 2013 to 2026). "IL-1β has been implicated in the regulation of inflammatory pathways that drive myocardial fibrosis and necrosis." (PMID 40427493, 2025). "The modest recovery of contractile function in anti-IL1β antibody-treated mice was associated with a substantial reduction in myocardial fibrosis." (PMID 39763850, 2024). "In an AMI mouse model, NLRP3 inflammasomes can activate the formation of IL-1β, cause myocardial damage and myocardial fibrosis, and directly inhibit the formation of NLRP3 inflammasomes." (PMID 33407160, 2021). "Pro-inflammatory mediators, such as transforming growth factor (TGF)-β1, tumor necrosis factor (TNF)-α and interleukin (IL)-1β amplify the inflammatory response and play pathogenic roles in myocardial fibrosis and remodeling." (PMID 24807380, 2014). "Persistent NF-κB activation promotes chronic low-grade inflammation, characterized by overexpression of TNF-α, IL-1β, and IL-6, which contributes to cardiomyocyte apoptosis and myocardial fibrosis." (PMID 41158877, 2025). "Urea directly activates NLRP3 inflammatory vesicles and stimulates monocytes to secrete IL-1β, driving coronary artery calcification and myocardial fibrosis." (PMID 40937404, 2025). "In mice with pressure-overload remodeling, cardiac NLRP3 inflammasome activation enhances greater myocardial fibrosis by the upregulation of TGF-β1 triggered by IL-1β." (PMID 40076547, 2025). "Researchers deleted cardiac fibroblasts’ IL-1 receptor and CCR2+ monocytes and macrophages’ IL-1β ligand and inhibited IL-1β signaling by a specific antibody, and results showed that myocardial fibrosis and cardiac function were well improved." (PMID 40564008, 2025). "And sterile inflammation is closely associated with the levels of pro-inflammatory factors (e.g., TNF-α, IL-6, and IL-1β) that can induce myocardial fibrosis." (PMID 40881586, 2025). "In mice subjected to permanent coronary artery occlusion, MCC950 improved cardiac remodeling by lowering myocardial fibrosis, caspase-1 activation, inflammatory cell infiltration, and IL-18 and IL-1β expression levels." (PMID 40079000, 2025). "IL1B also directly leads to myocardial fibrosis and tubulointerstitial damage in the kidneys by activating nuclear factor κB (NF-κB) and promoting the TGF-β signaling pathway." (PMID 40661082, 2025). "IL-1β plays an important role in adverse remodeling following cardiac injury and promotes myocardial fibrosis via a paracrine communication axis between inflammatory macrophages and fibrotic fibroblasts." (PMID 39763850, 2024). "In rats, cardiac function, serum levels of cardiac enzymes, apoptosis, myocardial fibrosis, and levels of IL-1β, IL-18, TNF-α, TLR2, and pyroptosis-related molecules were detected." (PMID 39018487, 2024). "Meanwhile, the accumulation of ROS leads to NLRP3 inflammatory vesicle activation and IL-1β production, which initiates a signaling cascade response that upregulates TGF-β1 transcription and causes myocardial fibrosis." (PMID 39444690, 2024). "Upon harvesting hearts from these cohorts, we assessed myocardial fibrosis and found a significant decrease in fibrotic area in anti-IL-1β antibody treated Dsg2mut/mut mice relative to isotype-treated counterparts." (PMID 39763850, 2024). "Proinflammatory cytokines such as tumor necrosis factor (TNF-α), interleukin 1β (IL-1β), and interleukin 6 (IL-6) can inhibit myocardial contraction, promote myocardial fibrosis, and increase collagen synthesis in pathological cardiac hypertrophy." (PMID 36270989, 2022). "MCC950 (10 mg/kg) administered three times in angiotensin II infusion-induced hypertension has been shown to reduce myocardial fibrosis and IL-1β levels." (PMID 33673188, 2021). "In mice with permanent coronary artery occlusion, MCC950 (10 mg/kg) reduced inflammatory cell infiltration, caspase-1 activation, IL-18 and IL-1β levels, and myocardial fibrosis, improving cardiac remodeling." (PMID 33673188, 2021).
Myocardial fibrosis (continued). "Activated NF-κB increases the expression of TGF-β1, TNF-α and IL-1β, which subsequently activates collagen deposition and myocardial fibrosis that lead to myocardial remodeling and HF." (PMID 24807380, 2014). "Inflammatory cytokines, including TGF-β1, TNF-α and IL-1β, play crucial roles in myocardial fibrosis and the pathological progression of left ventricular remodeling following MI." (PMID 24807380, 2014). "The pro-inflammatory cytokines, including TGF-β1, TNF-α, and IL-1β, play crucial roles in myocardial fibrosis and the pathological progression of LV remodeling by inducing inflammatory action via the NF-κB pathway." (PMID 24260217, 2013). "We critically examine how loss-of-function mutations in epigenetic regulators promote a pro-inflammatory macrophage phenotype through NLRP3 inflammasome activation and IL-1β/IL-6 signaling, thereby accelerating atherogenesis, plaque instability, and myocardial fibrosis." (PMID 42039360, 2026). "Concurrently, EMPA treatment effectively suppressed activation of the NF-κB/NLRP3 signaling pathway, accompanied by reduced levels of IL-1β and IL-18, suggesting decreased levels of cardiomyocyte pyroptosis and markedly alleviated inflammatory infiltration and myocardial fibrosis." (PMID 42099788, 2026). "The research demonstrated that the colchicine delivery system encapsulated in nanoparticles effectively reduced the levels of serum C-reactive protein (CRP), tumor necrosis Factor-alpha (TNF-α), and IL-1β, decreased the infarct area by 45%, and alleviated myocardial fibrosis." (PMID 41299461, 2025). "Interleukin-6, interleukin-1 beta and the tumour necrosis factor (TNF)-alpha may cause myocyte damage via the major histocompatibility complex-1, by local nitric oxide release and myocardial fibrosis." (PMID 36088383, 2022). "Although direct myocardial cell injection up-regulates cardioprotective factors in the myocardium, it also induces up-regulation of the proinflammatory cytokines, including IL1β, that adverse affect the contractile function of cardiomyocytes or serve to exacerbate myocardial fibrosis." (PMID 25860790, 2015). "In the male Wistar rats treated with 1 mg/kg of LPS for three weeks, thymoquinone at 2, 5, and 10 mg/kg doses also could improve myocardial fibrosis through decreasing the cardiac level of IL‐1β, TNF‐α, NO, and MDA, and enhancing the total thiol content and SOD and CAT activity." (PMID 39898124, 2025). "Taken together, IL-1β functions as a factor downstream of NLRP3 inflammatory vesicles and participates in the process of myocardial fibrosis by promoting the production of factors such as TGF-β1 and activating FGF-2 to promote End-MT." (PMID 40881586, 2025). "It reduced the expression of IL-6, IL-1β, and matrix MMP9, inhibited cell division and proliferation to inhibit myocardial fibrosis." (PMID 38469405, 2024). "Cytokines, including proinflammatory signaling IL-1β, IL-6, TNF-α, and myocardial fibrosis signaling TGF-β, were significantly reduced in the BZ." (PMID 35571187, 2022). "Metformin inhibited the activation of TNF-α, IL-6, IL-1β, and NLRP3 inflammasome, reduced the size of MI and myocardial fibrosis, enhanced the activity of myocardial cells, reduced the activity of LDH, inhibited pyroptosis and inflammation." (PMID 35509275, 2022). "It was shown that pinocembrin can inhibit pyroptosis by activation of Nrf2/Sirt3 signaling pathway, LVEF, LVFS, LVIDd, LVID, and myocardial fibrosis were improved, and the expressions of LDH, CK-MB, IL-1β, and IL-18 were reduced." (PMID 35509275, 2022). "Using mIF methods, we have demonstrated presence of IL-1B and IL6 activity within collagen fibers in the regions of myocardial fibrosis, both of which have been known to play a profibrotic role." (PMID 34765640, 2021). "Based on the previous studies and the present study, we suggest that the effect of ivabradine on myocardial fibrosis is related to the reduction of the proinflammatory cytokines TNF-α, IL-1β, and IL-6." (PMID 27847478, 2016).
Myocardial fibrosis (continued). "NF-κB contributes to myocardial fibrosis pathogenesis because it regulates genes/proteins important for disease progression, including cytokines (e.g., TNF-α), interleukins (e.g.,IL-1β)." (PMID 26846090, 2016). "In summary, BYHWD exerts anti-inflammatory effects by down-regulating the expression of inflammatory factors such as IL-6, IL-1β, IL-18, and NLRP3, and inhibiting the JAK/STAT and TLR4/NF-κB signaling pathways, thereby slowing down the process of myocardial fibrosis." (PMID 40881586, 2025). "IL-1β was identified as a key mediator in promoting the proliferation and differentiation of CFs into myofibroblasts, indicating that NLRP3 inflammasome activation is an important factor mediating the progression of myocardial fibrosis." (PMID 39925805, 2025). "The inflammatory cascade reaction mediated by neutrophil granulocyte and mononuclear macrophages is one of the common mechanisms leading to the myocardial fibrosis, which can secrete a variety of proinflammatory cytokines such as TNF-α, IL-1β, and IL-6, leading to the myocardial fibrosis." (PMID 36105253, 2022). "The results showed that B-cell deletion reduced the expression of the cytokines TNF-α, IL-1β, IL-6, and TGF-1β, decreased myocardial collagen synthesis after AMI, alleviated myocardial fibrosis, improved left ventricular remodelling, and maintained the left ventricular ejection fraction." (PMID 33407160, 2021). "Activated B cells promote cytokine (TNF-α, IL-1β, IL-6, TGF-1β) secretion and may participate in the pathological process of myocardial injury after AMI, which is related to myocardial fibrosis after AMI." (PMID 33407160, 2021). "It suppresses TNF-α and IL-1β synthesis by activating one of its target genes, the Suppressor of Cytokine Signaling (SOCS)-3, thus preventing from collagen synthesis by activated myofibroblasts and from myocardial fibrosis." (PMID 32117843, 2020). "Furthermore, the experimental results suggested that GZD could downregulate the expression levels of IL-6, IL-1β, CCL2, MMP-2, and MMP-9, thus inhibiting the inflammation and myocardial fibrosis in Dahl salt-sensitive rats." (PMID 33906674, 2021).
preeclampsia (57 papers, 2010 to 2025). Preeclampsia is a hypertensive disorder of pregnancy that is characterized by new-onset hypertension with proteinuria presenting after 20 weeks of gestation, and depending on mild or severe forms may initially present with severe headache, visual disturbances, and hyperreflexia. "Uric acid enhances trophoblast IL-1β production via activation of the NLRP3 inflammasome and production of IL-1β, which are implicated in the pathogenesis of preeclampsia and adverse pregnancy outcome." (PMID 36560538, 2022). "Preeclampsia is associated with increased maternal systemic inflammatory markers including total cholesterol, oxLDL, IL-1β and soluble fms-like tyrosine kinase-1 (sFlt-1)." (PMID 33117348, 2020). "A case-control study of 232 patients with preeclampsia and 447 healthy controls showed that IL-1β rs1143627 was associated with risk of preeclampsia in a Chinese Han population." (PMID 28676856, 2017). "The purpose of our study is to investigate the relationship between IL-1β -31C/T (rs1143627) and -511T/C (rs16944) polymorphisms and the preeclampsia (PE), and analyze the Linkage disequilibrium (LD) and haplotype frequency of the two polymorphism loci." (PMID 25222025, 2014). "Maternal circulating proinflammatory cytokines (IL-1β, TNFα) induced by infection or inflammation have previously been associated with preeclampsia." (PMID 20940111, 2011). "Furthermore, cytokines secreted by the M2b phenotype, including TNF‐α, IL‐1β, and IL‐6 have been associated with preeclampsia." (PMID 37269190, 2023). "High levels of interleukin‐1β (IL‐1β) are associated with preeclampsia." (PMID 31943890, 2020). "Furthermore, DAMP-induced NLRP3 levels have been extensively investigated in placental inflammation and dysfunction through the accumulation of cytokines (e.g., IL-1β), all of which were implicated in various pregnancy complications including preeclampsia and spontaneous pre-term labour." (PMID 35563719, 2022). "A recent study, showed that uric acid activates the inflammasome in trophoblast cells, leading to IL-1β secretion and, suggesting that it is a novel mechanism for induction of inflammation in the maternal-fetal interface and causing adverse pregnancy outcomes, including preeclampsia." (PMID 26053021, 2015). "Maternal platelet activation (P-selectin positive platelets) was linked with disease severity (sFlt-1/placental growth factor) and maternal plasma IL-1β and sVCAM-1 only in late-onset preeclampsia." (PMID 40746439, 2025). "This phenomenon resulted from higher cytokine concentrations (such as IL-12, TNF-α, and IL-1β) in early- versus late-onset preeclampsia." (PMID 38229046, 2024). "In this review, we summarized recent findings linking IL-1β to systemic arterial hypertension, pulmonary hypertension, and gestational hypertension." (PMID 34445357, 2021). "We prospectively examined a cohort of maternal-infant dyads with preeclampsia for maternal inflammatory cytokines at time of preeclampsia diagnosis and delivery, and fetal cord blood cytokines (IL-1β, IL-6, IL-8, and TNF-α)." (PMID 34780565, 2021). "In our study, Gcm-1 expression in human placentae was reduced in preeclampsia patients compared to healthy controls and negatively correlated with inflammasome marker cleaved IL-1β." (PMID 34576036, 2021). "Dramatic upregulation of TNF‐α, IL‐6, and IL‐1β was observed in placental tissues from preeclampsia patients compared to healthy donors." (PMID 34089575, 2021). "Preeclampsia with normal fetal growth was associated with increased expression of NLRP3 and IL-1β, particularly in decidual areas of close maternal-fetal interaction." (PMID 33117348, 2020). "In this study, we detected an association between preeclampsia and VEGFA and IL1β gene polymorphisms." (PMID 31943890, 2020). "For example, infection with Chlamydia trachomatis increases levels of IFN-γ in cervical secretions, the secretion of IL-1β and TNF-α in dendritic cells, and the risk of preeclampsia." (PMID 30448406, 2019).
preeclampsia (continued). "Not only the baseline release of pro-inflammatory cytokines from peripheral blood monocytes was increased in preeclampsia, LPS-induced TNF-α, IL-1β, and IL-6 release was also enhanced in women with preeclampsia." (PMID 31138166, 2019). "There is evidence that placentas from preeclampsia patients secrete more IL-1β compared to normotensive placentas." (PMID 31434191, 2019). "Studies have shown high IL-1β and TNF-α concentration in serum or amniotic fluid are associated with adverse pregnancy outcomes, including first-trimester losses, preeclampsia and gestational diabetes mellitus, and preterm birth." (PMID 27978823, 2016). "In the present study, the demonstrated capacity of NLRP3 inflammasome in inducing IL-1β production suggests a role for this mechanism in the systemic inflammatory response observed in preeclampsia." (PMID 26053021, 2015). "The biochemical data from this study relating to the inflammatory mediators TNF-α and IL-1β and the preeclampsia biomarkers sFlt-1 and PlGF are also worthy of note." (PMID 24586695, 2014). "IL-1β is a pivotal component of the proinflammatory response that can be harmful to the host, but the report of altered serum IL-1β levels in women with preeclampsia remains controversial." (PMID 24586695, 2014). "The cytokines TNF-α and IL-1β are primarily produced by macrophages and in preeclampsia participate in abnormal extravillous trophoblast invasion." (PMID 24586695, 2014). "Interestingly, increased maternal first trimester circulating levels of IL-1β have been reported in pregnancies that go on to develop early-onset preeclampsia." (PMID 37468163, 2023). "On the other hand, first trimester IL-1β concentrations have been linked to preterm birth associated with preeclampsia (<37 weeks), but not with those who only developed preeclampsia." (PMID 33680514, 2021). "Others, however, reported that IL-1β was significantly higher or lower in women with preeclampsia." (PMID 33680514, 2021). "Overall, IL-1β may be an early predictor for preeclampsia resulting in preterm delivery albeit more research is needed." (PMID 33680514, 2021). "Growing evidence supports the clinical benefits and anti-inflammatory effects of drugs targeting the NLRP3 inflammasome and IL-1β pathway in several diseases, but whether they are pregnancy-safe and effective in preeclampsia needs to be determined." (PMID 33117348, 2020). "Polymorphisms in IL1β and VEGFA were associated with preeclampsia in this setting." (PMID 31943890, 2020). "These authors therefore suggested that the placenta may be a source of elevated maternal serum IL-1β in preeclampsia." (PMID 24586695, 2014). "Preeclampsia is associated with an exacerbated inflammatory response that may lead to a release of pro-inflammatory cytokines, including TNF-α, interleukin-6 (IL-6), interleukin-8 (IL-8), and interleukin-1 beta (IL-1β)." (PMID 40109359, 2025). "There is emerging evidence for elevated placental inflammasome activation in early-onset preeclampsia; thus, we hypothesized that IL11 would activate placental inflammasomes resulting in cleaved IL1β, pyroptosis, and initiation of the cascade of events leading to preeclampsia." (PMID 37292200, 2023). "Furthermore, in maternal samples obtained in the second trimester (approx. 17 weeks), IL-1β is reportedly higher in healthy pregnancy compared to women who developed preeclampsia, with higher IL-1β concentrations in the second trimester associated with decreased odds of developing preeclampsia." (PMID 33680514, 2021). "There are few published data regarding the association of VEGFA and IL1β polymorphisms with preeclampsia, and there are no published data regarding the association of VEGFA and IL1β polymorphisms were preeclampsia in sub‐Saharan African populations, including in Sudan." (PMID 31943890, 2020).